SMAD3 (SMAD family member 3)
Diseases named in the same sentence as SMAD3 in open-access papers (continued):
Sharing a sentence is not in itself a finding about the gene and the disease.
cancer (433 papers, 2006 to 2026). A tumor composed of atypical neoplastic, often pleomorphic cells that invade other tissues. "Aberrant SMAD3 activation is thought to be a driving event for cancer metastasis, but the underlying mechanism remains elusive." (PMID 40164592, 2025). "In advanced tumours, TGF‐β transforms into a pro‐cancer factor through pathways such as AKT and C‐jun/SMAD3, further promoting angiogenesis, immune evasion and activation of Cancer‐Associated Fibroblasts (CAFs)." (PMID 40847555, 2025). "As the main member of R-Smads and a hallmark protein in the TGF-β/Smads signaling pathway, Smad3 has been implicated in diverse biological processes, including energy metabolism, embryonic development, fibrosis, and cancer progression." (PMID 38690917, 2024). "Knockdown (KD) of BAZ1A triggered senescence-associated phenotypes in various human cancer cell lines due to increased SMAD Family Member 3 (SMAD3) expression promoting p21 activation." (PMID 39112459, 2024). "TGF-β receptor–regulated SMADs: SMAD2 and SMAD3, are ubiquitous and constitutive in normal cells in general, whereas their loss is frequently observed in various cancers." (PMID 38960622, 2024). "Macrophage‐myofibroblast transition (MMT) is a newly discovered pathway for mass production of pro‐tumoral cancer‐associated fibroblasts (CAFs) in non‐small cell lung carcinoma (NSCLC) in a TGF‐β1/Smad3 dependent manner." (PMID 37967345, 2024). "Top expressed cancer-implicated gene targets for each TF converged on notable genes involved in cell signaling (SMAD3, PTPRJ), BCL6 regulation (FBXO11, BCOR), and transcriptional regulation (RUNX1, ERG, CUX1)." (PMID 38116118, 2023). "Chronic UV exposure causes TGFβ1/Smad3 signaling activation which contributes to cancer progression by regulating many physiological processes, including cancer cell proliferation, and invasion." (PMID 37762344, 2023). "Conversely, MSI2 is a crucial regulator of cancer stem cell programs by acting on the stability and translation of target mRNAs that encode key proteins of oncogenic signaling pathways (e.g., TGFβR1/SMAD3, NUMB/Notch, PTEN/mTOR, MET, and MYC)." (PMID 37107676, 2023). "Stromal VCAN immunostaining can indicate TGFβ-activated stroma, as it was exclusively stained in the cancer stroma, mainly expressed by CAFs in association with phospho-SMAD3 staining." (PMID 37894310, 2023). "The deletion of ATOH8 is one of the key mechanisms underlying the transition of SMAD3 from cancer suppression to cancer promotion." (PMID 37685308, 2023). "In cancers, SMAD3 gene mutations are rare and are identified in colorectal adenocarcinomas, choriocarcinomas, and rarely in pancreatic ductal adenocarcinomas and appendiceal cancers, including mucinous neoplasms of the appendix, with possible loss of function." (PMID 37509254, 2023). "Several studies revealed the correlations between mutations of SMAD family proteins (Smad2, Smad3, Smad4 and Smad7) and various diseases and cancers, with the intracellular signal transduction molecule proteins (SMAD) in the TGF-β pathway." (PMID 37742025, 2023). "Second, we have clarified before that the TGF-β/Smad3 pathway, which is associated with the development of some human cancers, can be activated via persistent transactivation of EGFR after ARAP1 regulation." (PMID 35291911, 2022). "SMAD3 plays a central role in cancer metastasis, and its hyperactivation is linked to poor cancer outcomes." (PMID 35085106, 2022). "In concordance, bioinformatic analysis of the upregulated TGF‐β1/Smad3‐dependent transcriptomes of MMTs from our previous study found a close association with cancer in contrast to the tissue fibrosis." (PMID 34791825, 2022). "TOP2A silencing reduces the phosphorylation of Smad2 and Smad3 and impairs the malignant characteristics of cancer cells, which is implicated in the carcinogenesis of high-grade serous OC." (PMID 34787052, 2021).
cancer (continued). "In fact, Smad7 suppression is associated with and resulted in Smad3 activation in inflammatory diseases including cancer." (PMID 34514726, 2021). "Aberrant SMAD3 activation has been implicated as a driving event in cancer metastasis, yet the underlying mechanisms are still elusive." (PMID 34392614, 2021). "The up-regulation of AXL causes the phosphorylation of Smad3, which is regulated by TGFβ signaling and is well correlated with an increase in the metastasis of cancer." (PMID 32324796, 2020). "Our approach using distinct cell lines identified characteristic APA profile changes in several cancer relevant genes including SMAD3, PA2G4 and MTHFD1L and linked the latter two to the de-regulation of hnRNPC in metastatic site-derived cells." (PMID 31147722, 2019). "A previous study demonstrated that JNK participated in SMAD3 Ser208 phosphorylation, and this phosphorylation contributes to the SMAD3 activation and causes cancer progression." (PMID 29499695, 2018). "We selected 6 genes (MUC4, MUC13, MUC20, BMP7, AKT3, and SMAD3) that were closely associated with the development and progression of cancer to validate the conclusions drawn from the gene expression profiling analysis." (PMID 26673820, 2016). "Rad23A was connected via the nodes p300 and CBP to the other nodes in the network, whereas Smad3 was connected to a variety of nodes which also included important cancer-associated TFs such as c-Myc, Runt-related factors, and Smad factors." (PMID 27092172, 2016). "Genetically, Smad2 and Smad4 are frequently mutated or deleted in certain human cancers whereas Smad3 mutation or deletion is infrequent." (PMID 22204491, 2011). "Evidence also supports that the hyperactivation of Smad3 is associated with poor cancer prognosis." (PMID 38675493, 2024). "Besides immune cells, cancer associated fibroblasts (CAFs) induces EMT in human NSCLC cells through Smad3 activation." (PMID 37205317, 2023). "As a member of Smad family, SMAD3 plays an important role in cancer progression, and its mutations status and DNA methylation level were related to the development of various kinds of cancers." (PMID 34434896, 2021). "Based on these evidence‐based observations, Smad3 may play a pathogenic promoter in cancer, whereas Smad7 may be protective." (PMID 34514726, 2021). "Furthermore, Smad3 gene deficiency can affect immune regulation, promote inflammation and drive cancer progression." (PMID 32406200, 2020). "Smad3‐deficient mice are prone to cancer, including colon cancer and skin cancer." (PMID 32406200, 2020). "The therapeutic potential of Smad3-targeted therapy for cancer treatment is also implicated." (PMID 28262747, 2017). "It has now been confirmed that the alteration of Smad3 expression could cause the occurrence and development of cancer." (PMID 27655675, 2016). "SERPINE1 is fundamentally located in extracellular region of cell and plays important roles such as protease binding in which is mainly involved in chronological cell aging and angiogenesis, complement and coagulation cascades and loss of function of SMAD2 and SMAD3 in cancer." (PMID 28228815, 2016). "Based on these clues, the Smad3 linker region phosphorylation (pSmad3L) closely associates with cancer progression, although the detailed cellular signaling mechanisms responsible for the phosphorylation and its biological significance have not been fully understood." (PMID 26497676, 2015). "Mutation of the Smad3 gene is very rarely found in human cancer." (PMID 24047375, 2013).
cancer (continued). "Interestingly, well-known cancer-associated TFs like c-Fos, c-Jun, Smad3, and c-Ets-2 exhibited rather constant levels of upregulation throughout tumorigenesis." (PMID 21464922, 2011). "Studies have shown that the phosphorylation state of SMAD3 is associated with increased proliferation, migration, and invasion of cancer cells, and its acetylation and methylation modifications are also related to increased invasiveness and metastasis of cancer cells." (PMID 40466864, 2025). "In addition, Smad2 mutations are found in various cancers at a low frequency, whereas Smad3 mutations are rare and could be found only in colon cancers." (PMID 36549646, 2022). "Indeed, within lung endothelial cells, we observed strong enrichment of cancer associated DNAm changes at binding targets of SMAD2/SMAD3, transcription factors that are known to be indispensable for vascular stability and integrity and which mediate TGF-beta induced EndoMT in cancer." (PMID 32883324, 2020). "Expressions of fibronectin and PD-L1 were screened in TEVs and the mRNA levels of vimentin and SMAD3 were also assessed in cancer cells after TEV co-culturing." (PMID 40725070, 2025). "The Jag1-ICD/SMAD3–TWIST1 axis represents a novel regulatory pathway that promotes invasive phenotypes in cancer cells, driving brain tumor invasion through a mechanism distinct from canonical TGF-β signaling." (PMID 41294868, 2025). "The SMAD3/4 complex, in association with SNAI1, represses E-cadherin expression and enhances N-cadherin expression, thereby promoting EMT in cancer cells." (PMID 40134588, 2025). "EZH2, which is activated in cancers, promotes the methylation of Smad3, facilitating the recruitment of Smad3 to SARA and Smad3′s subsequent activation by TβRI." (PMID 38675493, 2024). "Such Smad2 or Smad3 specificity downstream of TGFβ signaling has been reported in the context of other cancer-related mechanisms." (PMID 38201651, 2024). "NcRNAs interact with TGF-β/SMAD3 signaling to regulate important facets of cancer cell development, including EMT, invasion, migration, cancer cell stemness, and metastasis." (PMID 38279330, 2024). "But this immunosuppressive effect was countered by the potent immunostimulatory functions of NK-derived GM-CSF, as silencing GM-CSF markedly impaired the anti-cancer effects of Smad3 knockout NK cells." (PMID 38878186, 2024). "Altogether, silencing GM-CSF in Smad3 knockout NK cells remarkably mitigated the therapeutic effects of Smad3 knockout NK cell therapy, highlighting the significance of GM-CSF in NK-mediated anti-cancer effects." (PMID 38878186, 2024). "The dysregulation of TGF-β signaling is implicated in cancer progression, and CBP/p300’s involvement in modulating SMAD3-dependent transcription suggests a therapeutic avenue for targeting cancers with altered TGF-β activity." (PMID 39407454, 2024). "Taken together, on top of directly promoting NK cell-mediated cytotoxicity against cancer cells, blocking Smad3 augmented the immunostomulatory effects of NK cells by enhancing the production of GM-CSF." (PMID 38878186, 2024). "SMAD3 belongs to the subclass of facilitated SMADs via forming SMAD 2/3/4 complex in several types of cancer to function in TGF-β signaling." (PMID 38641828, 2024). "Silencing Smad3 remarkably restores the cytotoxicity of NK-92 against cancer in TGF-β-rich microenvironment, but its effects on the immunoregulatory functions of NK cells remain obscure." (PMID 38878186, 2024). "Similar to neutrophils, Smad3 has been identified as a regulator for the transition; targeting Smad3 offers a potential therapeutic strategy to suppress cancer progression." (PMID 39759220, 2024). "These alternative pathways included c-Myc, WNT, AKT, STAT3 and SMAD3; all of which have important roles in tumourigenesis and cancer progression." (PMID 38195591, 2024). "TGILR expression was directly activated by the canonical TGFbeta/SMAD3 signaling axis, and this activation is highly conserved in cancer." (PMID 38806480, 2024).
cancer (continued). "For example, miR-21 targets Smad7, an inhibitor of TGF-β/SMAD3 signaling, which leads to enhanced cell proliferation and invasion in various cancers." (PMID 38279330, 2024). "Noticeably, SMAD3 serves as a key TF involved in LIF transcription in both cancer cells and CAFs via different regulatory models." (PMID 39206755, 2024). "Epigenetic regulation of SMAD3 via histone modifications plays important roles in cancer progression and metastasis." (PMID 38279330, 2024). "Smad3 is often rendered inactive in the malignant haematological conditions, which leads to a more significant proliferation of cancer cells." (PMID 37742025, 2023). "The deregulation of either KLF17 or SMAD3 would diminish the ability of TGF-β to inhibit cancer cells." (PMID 36761967, 2023). "Mutations in the SMAD2, SMAD3, and SMAD4 genes are associated with cancers of the intestine, pancreas, or appendix." (PMID 37509254, 2023). "At the same time, SEC63 induces Snail1 expression by increasing acetylation of SMAD3 to promote cancer cell metastasis." (PMID 37122003, 2023). "Treatment with SB431542 also reduced rhTGF-β1- and MDA231-sEV-induced TGF-β/SMAD3 signaling activity in cancer cells." (PMID 38105247, 2023). "On the other hand, increased expression of SMAD3, SMAD5, SMAD6, and SMAD7 was associated with low OS in stage I and II of the cancer." (PMID 37685308, 2023). "KLF17 is a crucial regulator of TGF-β signaling, which forms a positive feedback loop with SMAD3, and the expression of both is often positively correlated in cancer tissues." (PMID 36761967, 2023). "Whereas cancer cells infected with control adenovirus showed increased TGF-β/SMAD3 signaling activity in response to both rhTGF-β1 and MDA231-sEVs, this effect was dramatically impaired in SMAD7-overexpressing cancer cells." (PMID 38105247, 2023). "SMAD family member 3 (SMAD3) is a key molecule in the regulation of cancer metastasis-related genes, such as ZEB, Twist family genes, and Snail, via the formation of the TGF-β-induced SMAD 2/3/4 complex in several types of cancer." (PMID 37121971, 2023). "Previous studies have shown that the AKT/GSK3β/c-Fos/NFATc1, IGF-1/AKT/NF-κB (RelA) or TGF-β/Smad3/4 signaling cascade play a key regulatory role in BMM of many cancers." (PMID 37337244, 2023). "Another study in cultured hepatocyte progenitor cells found that inhibition of SMAD3-mediated gene expression downstream of TLR4 contributed to the induction of cancer stem cell properties." (PMID 37685308, 2023). "Myocardin and SMAD3/SMAD4 form a positive feedback loop that drives TGF-β-induced EMT in NSCLC cancers." (PMID 37685308, 2023). "This was evident in both the Smad3-KO mice, and with an increased number of TANs following the adoptive transfer of Smad3-KO versus Smad3-WT-BMDN in the LLC cancer model." (PMID 37002229, 2023). "Collectively, we identified the JICD1/SMAD3-TWIST1 axis as a novel inducer of invasive phenotypes in cancer cells." (PMID 38092725, 2023). "In conclusion, TGF-β1/SMAD3 signaling has become a potential therapeutic target in diverse cancers that should be tested in future studies." (PMID 37273004, 2023). "Smad3-silence strategy is an enhanced immunotherapy in cancers, and targeting Smad3/Smad7 enhances NK cells’ functions in anti-cancer immunity." (PMID 36765396, 2023). "In CRC, SMAD3 reduces its expression through miR-4429 and ultimately inhibits the occurrence, development, and metastasis of cancer cells." (PMID 36969909, 2023). "Collectively, these findings reveal the complicated layers involved in the regulation of SMAD3 activation coordinated by EZH2-mediated SMAD3 K53/K333 methylation to drive cancer metastasis." (PMID 35085106, 2022). "SMAD3 promotes cancer progression by inhibiting natural killer (NK) cells, and SMAD3-silenced NK cells can enhance cancer immunotherapy." (PMID 36157222, 2022).
cancer (continued). "These pathways include mitogen-activated protein kinase 1 (MAPK1), which inhibits apoptosis and promotes cancer cell proliferation, or small mothers against decapentaplegic homolog 3 (SMAD3) required in the epithelial-mesenchymal transition (EMT) process." (PMID 35008915, 2022). "SMAD2 expression correlated negatively and SMAD3 expression positively with the invasive capacity of cancer cells, both in vitro and in vivo." (PMID 35681731, 2022). "Although a growing body of evidence indicates that each SMAD can play distinct roles both in vitro and in vivo, very few studies have concomitantly compared the individual roles of SMAD2 and SMAD3 in cancer progression." (PMID 35681731, 2022). "Specifically, KDM6B, RGS19, and SMAD3, which belong to beta-catenin binding in the gene ontology, were up-regulated during the process of cancer plasticity." (PMID 35673567, 2022). "LINC02470 and SMAD3 were more highly expressed in high-grade cancer cells with higher mesenchymal-like traits, such as higher N-cadherin and vimentin expression but lower E-cadherin and cytokeratin 18 expression." (PMID 35205713, 2022). "To next evaluate the impact of SMAD2 or SMAD3 modulation on the invasive properties of cancer cells in hypoxia, we compared the capacity of HT-1080 and MDA-MB-231 knockdown cells to produce invadopodia under normoxic versus hypoxic conditions." (PMID 35681731, 2022). "We described herein the dichotomous role of SMAD2 and SMAD3 in the ability of cancer cells to form invadopodia and to produce spontaneous metastasis." (PMID 35681731, 2022). "Next, we studied the relationship between SMAD3 methylation expression levels and the overall survival of patients with cancer." (PMID 35085106, 2022). "In line with our notion, we demonstrated that macrophage-specific inhibition of Smad3 effectively blocked MNT and the cancer-associated spontaneous nocifensive behaviors in mice." (PMID 36206343, 2022). "Altogether, these results support a role for ITGB2 and VIM in the SMAD3-dependent pro-invasive properties of cancer cells that are accentuated by hypoxic conditions." (PMID 35681731, 2022). "As a result, our study not only uncovered the oncogenic role of RAB26 in NSCLC, but also identified a novel target for SMAD3-mediated cancer progression." (PMID 35291909, 2022). "Combining TAT peptides 1 and 2 markedly inhibited EZH2-mediated SMAD3 K53/K333 methylation, as well as cancer cell EMT." (PMID 35085106, 2022). "By applying our experiences from tissue inflammation into cancer, we have identified a Smad3-dependent TME that is critical for promoting cancer progression." (PMID 36206343, 2022). "In the present study, we described how hypoxia selectively induced the pro-invasive arm of TGFβ signaling through activation of a HDAC6- SMAD3-SARA-ITGB2/VIM pathway that contributes to the ability of cancer cells to invade and form metastases." (PMID 35681731, 2022). "Macrophage-specific silencing of SMAD3 effectively blocks macrophage–myofibroblast transition (MMT), thereby inhibiting cancer-associated fibroblasts (CAF)-mediated cancer progression." (PMID 35291909, 2022). "In this study, we sought to determine the mechanism by which hypoxia regulates SMAD3 signaling in cancer and how this affects cancer progression and metastasis." (PMID 35681731, 2022). "On the other side, TF SMAD3 was identified to involve in cancer progression by regulating its target genes BECN1, GLI2, and E4BP4." (PMID 33802957, 2021). "A total of 60 CRC TFs were obtained, among which SMAD3 were present in five types of common malignant tumors, while 46 CRC TFs including NR5A1 were only present in one type of malignant tumor." (PMID 34722892, 2021). "Recently, we discovered the essentialness of Smad3 in the microenvironment for developing inflammatory diseases including cancer." (PMID 34514726, 2021). "Although many studies have reported that dysregulated SMAD3 is involved in cancer progression, its role in CRC needs further exploration." (PMID 33754062, 2021).